AJAP1 (adherens junctions associated protein 1)
Diseases named in the same sentence as AJAP1 in open-access papers (continued):
Sharing a sentence is not in itself a finding about the gene and the disease.
Bladder Cancer (2 papers, 2020 to 2021). "The association between adherens junction-associated protein 1 (AJAP1) protein levels and clinicopathological features of urinary bladder cancer (UBC) patients." (PMID 32528872, 2020). "In addition, the silencing of TET1 reduced 5hmC levels and promoted cell proliferation by down-regulating the expression of AJAP1 in bladder cancer cells." (PMID 34852853, 2021).
diabetes (2 papers, 2024 to 2025). "Novel VaD loci were associated with hypertension, diabetes, and neuron maintenance (SPRY2, FOXA2, AJAP1, and PSMA3)." (PMID 39046104, 2024).
liver cancer (2 papers, 2021). An epithelial or non-epithelial malignant neoplasm that arises from the liver. "Previous studies have demonstrated that miR-552 functions as a potential oncogene in a series of cancer types and figure out several downstream targets, such as AJAP1 in liver cancer, Smad2 and DACH1 in colorectal cancer, TIMP2 and WIF1 in osteosarcoma 28-32." (PMID 33867818, 2021).
lung carcinoma (2 papers, 2013 to 2018). "Also, AJAP1 was correlated with susceptibility in lung cancer." (PMID 24369052, 2013).
neuroblastoma (2 papers, 2011 to 2016). Neuroblastoma (NB) is the most common solid, extracranial childhood tumor. "AJAP1, a putative neuroblastoma tumor suppressor gene, was the most centromeric disrupted gene in a case of T-cell ALL (case 136) and in a case of MZL (case 052) with unbalanced rearrangements." (PMID 22039459, 2011).
bladder tumor (1 paper, 2020). "In conclusion, our study demonstrated for the first time that TET1 may function as a tumor suppressor gene in UBC and AJAP1 plays a crucial role in TET1 suppression of bladder tumor growth through modulation of the Wnt/β-catenin signaling, affecting its downstream target genes." (PMID 32528872, 2020).
COVID-19 (1 paper, 2023). A disease caused by infection with severe acute respiratory syndrome coronavirus 2. "None of identified significant SNPs (in the intron of AJAP1 and the intron of FIG4) and none of the missense variants with a potential causal function on a severe outcome of COVID-19 (in the exon of PM20D1 and the exon of LRP4), found in our study, have been previously associated with COVID-19." (PMID 36662838, 2023).
dental caries (1 paper, 2014). The decay of a tooth, in which it becomes softened, discolored, and/or porous. "Dental caries’ GWAS identified significant signals in LYZL2, AJAp1, and KPNA4; and efforts are ongoing to identify genetic factors for multiple caries phenotypes." (PMID 24702466, 2014).
epilepsy (1 paper, 2024). A brain disorder characterized by episodes of abnormally increased neuronal discharge resulting in transient episodes of sensory or motor neurological dysfunction, or psychic dysfunction. "Now, we have identified several individuals with AJAP1 variants who have epilepsy and/or neurodevelopmental phenotypes." (PMID 38985877, 2024). "Using exome sequencing and chromosomal microarray analysis, we have identified five individuals with monoallelic variants or a deletion in AJAP1, who present with epilepsy, neurodevelopmental problems, or intellectual disability." (PMID 38985877, 2024). "More recently, we identified two additional individuals with epilepsy and/or neurodevelopmental phenotypes who carry an AJAP1 splice variant (CADD score 35) or a deletion (individuals 4 and 5)." (PMID 38985877, 2024). "We have identified several monoallelic AJAP1 variants in individuals with epilepsy and/or neurodevelopmental disorders." (PMID 38985877, 2024). "While AJAP1 has primarily been studied in the context of cancer, AJAP1 has also been hypothesized to contribute to the development of epilepsy and/or neurodevelopmental disorders." (PMID 38985877, 2024).
lymph node metastasis (1 paper, 2022). "Multivariate analysis showed that AJAP1-Ezrin+, histological grade, and lymph node metastasis were risk factors for OS (p = 0.021, p = 0.005, and p < 0.0001)." (PMID 35311087, 2022).
malignant glioma (1 paper, 2022). A grade III or grade IV glioma arising from the central nervous system. "The loss of AJAP1 expression (caused by deletion or methylation) was associated with poor clinical outcome in patients with malignant gliomas." (PMID 35628499, 2022).
ovarian carcinoma (1 paper, 2021). A malignant neoplasm originating from the surface ovarian epithelium. "The genes with lower expression in HBCa.MEC are related to AJAP1(a tumor suppressor), HBG2 (down-regulated in ovarian cancer) and CBPE(a modulator of actin filaments’ organization)." (PMID 34445568, 2021).
tumor (23 papers, 2016 to 2025). "Within a region of 1p36.32, adherens junction-associated protein-1 (AJAP1) encoding an integral membrane protein has been considered as a tumor suppressor." (PMID 35628499, 2022). "Of these 13 gene candidates, three genes are already known to be tumor suppressor genes —adherens junctions associated protein 1 (AJAP1), GATA binding protein 5 (GATA5), and lecithin retinol acyltransferase (LRAT)." (PMID 33920410, 2021). "We found that AJAP1 protein level was significantly associated with T stage (p = 0.003) and tumor grade (p = 0.017)." (PMID 32528872, 2020). "Adherent junction associated protein 1 (AJAP1), a typical molecule of adherent junctions, has been found to be a tumor suppressor in many cancer types." (PMID 31171012, 2019). "In HCC and ESCC, the expression of AJAP1 was also found to be reduced due to promotor hyper-methylation and loss of copy number, suggesting that AJAP1 acts as a tumor suppressor." (PMID 28483980, 2017). "The aberrant expression of AJAP1 is associated with alterations in cell migration, invasion, increased tumor growth, and tumor vascularization, suggesting AJAP1 as a putative tumor suppressor." (PMID 28483980, 2017). "Based on our results and those of other authors, we suggest AJAP1 as a novel tumor suppressor and diagnostic marker." (PMID 28483980, 2017). "Similar to PKP1, CTNNA1, catenin cadherin-associated protein, alpha 1 (GeneBank: 1495) and AJAP1, adherens junctions associated protein 1 (GeneBank: 55966) expression levels are correlated with advancing tumor stage and inversely related to cell proliferation." (PMID 29052507, 2017). "Increased tumor vascularization and invasion inversely correlate with the mRNA levels of AJAP1, indicating that AJAP1 is important for cell and tissue integrity and that loss of AJAP1 promotes tumor progression." (PMID 28483980, 2017). "Shrew-1, also called AJAP1, is a transmembrane protein associated with E-cadherin-mediated adherence junctions and a putative tumor suppressor." (PMID 27870635, 2016). "Altogether, these findings support the idea that the SHREW-1/AJAP1 gene encodes functionally important protein(s) involved in regulatory protein circuits whose alterations contribute to tumor development and to so far unknown physiological processes." (PMID 27870635, 2016). "Adherens junction-associated protein 1 (AJAP1), a putative tumor suppressor downregulated in GPs based on mRNA NGS, is an experimentally validated target of hsa-miR-196a-5p." (PMID 40143207, 2025). "In GBM, AJAP1 levels are frequently reduced or lost, disrupting normal cell adhesion and enhancing tumor cells’ mobility and invasiveness." (PMID 39936963, 2025). "Ajap1 is a structural protein involved in numerous human malignancies and correlates with tumor growth and survival." (PMID 38594255, 2024). "In a GEO dataset, we found AJAP1 was downregulated in UBC tissues and its expression level was negatively correlated with overall survival in UBC patients, suggesting a putative tumor-suppressive role of AJAP1 in bladder carcinogenesis." (PMID 32528872, 2020). "Ajap1, contained in chromosomal region 1p36, was found to be frequently deleted in neuroblastoma and oligodendroglioma and thus represents a tumor suppressor gene in these tumors." (PMID 31511635, 2020). "The AJAP1/β-catenin KD group had the lowest tumor capacity and tumor growth rate among the three groups." (PMID 31171012, 2019). "More importantly, β-catenin localization and tumor progression also positively fed back on EGF/EGFR-attenuated AJAP1 expression." (PMID 31171012, 2019). "The RT‐qPCR results from the 81 pairs of HCC and adjacent tissues showed that AJAP1 had significantly higher expression in tumour‐adjacent tissues than in HCC tissues (P < 0.0001)." (PMID 30597727, 2019).
tumor (continued). "Our research, together with previous studies, shows that tumor growth behavior and vascularization are strongly influenced by AJAP1, hence suggesting AJAP1 as a tumor marker for the malignancy of different cancer types." (PMID 28483980, 2017). "According to these analyses, shrew-1 (also called AJAP1) is a tumor suppressor whose gene becomes hypermethylated and thus epigenetically silenced in the course of tumor development." (PMID 27870635, 2016). "Thus, loss of AJAP1 expression, observed in over 80% of primary GBM cases, was shown to enhance tumor cell invasion." (PMID 40565099, 2025). "Studies in many cancers found that the abnormal expression of AJAP1 is related to cell migration, invasion, increased tumour growth, and changes in tumour vascularisation, thus suggesting that AJAP1 may be a tumour suppressor." (PMID 36291586, 2022). "In ESCC, AJAP1 might serve as a tumor suppressor and that AJAP1 transcription is modulated by hypermethylation." (PMID 35646092, 2022). "We also examined whether AJAP1 is a critical regulator of TET1-induced tumor suppression and inhibition of Wnt/β-catenin pathway." (PMID 32528872, 2020). "Overexpression of miR‐552 promoted tumour growth, but overexpression of AJAP1 inhibited it." (PMID 30597727, 2019). "Knockdown of EGFR and AJAP1 promoted tumor growth and β-catenin nuclear expression." (PMID 31171012, 2019). "The tumor size and vascular invasion inversely correlate with AJAP1 mRNA levels in HCC." (PMID 28483980, 2017). "Therefore, we presumed that AJAP1 may have prevented tumor malignant behavior by inhibiting Ezrin expression." (PMID 35311087, 2022). "However, the effect of TET1 was not fully rescued by AJAP1 depletion, indicating other mechanisms involved in tumor suppression of TET1." (PMID 32528872, 2020). "Yet, it is not known whether the expression of AJAP1 is altered in the tumor cells and/or the vascular system, or whether the communication between cell types is involved." (PMID 28483980, 2017). "There is a negative correlation between AJAP1 and EGFR expression: as AJAP1 decreases, EGFR activity increases, promoting aggressive tumor behavior." (PMID 39936963, 2025).
cancer (13 papers, 2004 to 2025). A tumor composed of atypical neoplastic, often pleomorphic cells that invade other tissues. "And some identified 3′-UTR piSNV-affected genes, such as SLC6A11, NUDCD2, CTNNA3, RAB3C, and AJAP1, are well-studied cancer/disease related genes with a high deleterious mutation rate." (PMID 35654793, 2022). "Deletion or epigenetic silencing, caused by hyper-methylation of the proximal promoter as shown in glioblastoma tumors, leads to loss of AJAP1 and is associated with cancer development." (PMID 28483980, 2017). "We also found five genes discovered by the consensus DEA and PCA and annotated as candidate cancer genes in NCG: AJAP1, CD1B, CDH2, PABPC4L, and PCDH10." (PMID 40788820, 2025). "A number of studies on AJAP1 vital function in a variety of types of cancer have attracted people’s attention." (PMID 35311087, 2022). "The downregulation of TET1 and its direct target gene AJAP1 promotes cancer progression via activation of β-catenin signaling." (PMID 32528872, 2020). "In addition, GOBO dataset demonstrated that the expression of AJAP1 was related with cancer subtypes (p = 0.00402) and grades (p = 0.00275)." (PMID 31171012, 2019). "However, it remains to identify the regulation of AJAP1 in cancer development." (PMID 32528872, 2020). "The analyzed genes in this work (SOX17, MYOD1, MAGI2, CDH1, AJAP1, MGMT, CDH13, and RASSF1A) participate in essential biological processes to maintain cell normality, and there is sufficient evidence for their protective role against the development of cancer." (PMID 34991696, 2022). "When stratified by histology, POU4F3 and AJAP1 methylation testing did not miss any invasive cancer patients." (PMID 26300990, 2015).
brain diseases (1 paper, 2024). "Adherens junction–associated protein 1 (AJAP1) has been implicated in brain diseases; however, a pathogenic mechanism has not been identified." (PMID 38985877, 2024).
AJAP1 also shares sentences with these, for which no sentence is quoted: esophageal cancer (3 papers); endometrial cancer (2); esophagus carcinoma (2); Hypertension (2); neurodevelopmental disorder (2); prostate carcinoma (2); B-cell CLL (1); colorectal cancer (1); diffuse astrocytoma (1); Epileptic encephalopathy (1); gastric cancer (1); Global developmental delay (1); hematological malignancies (1); migraine (1); osteosarcoma (1); pancreatic cancer (1); Rett-like syndrome (1); scoliosis (1); T-cell ALL (1).